SLC7A11 (solute carrier family 7 member 11)
Diseases named in the same sentence as SLC7A11 in open-access papers (continued):
Sharing a sentence is not in itself a finding about the gene and the disease.
tumor (continued). "Interestingly, results indicate that SAS treatment increased transferrin and STEAP-3 expression, while decreased ferritin, SLC7A11, and GPx-4 expression, which are the major drivers that protect the tumor cells from ferroptosis." (PMID 39513121, 2024). "It was also found that glucose transporter inhibitors could induce cell death in SLC7A11-high cancer cells via disulfidptosis and inhibit SLC7A11-high tumor proliferation." (PMID 38671348, 2024). "Furthermore, researchers noted that glucose transporter inhibitors triggered disulfidptosis in tumor cells with elevated SLC7A11 expression, consequently impeding tumor growth." (PMID 38317842, 2024). "Increased SLC7A11 expression promotes tumor growth by suppressing ferroptosis levels." (PMID 38831301, 2024). "We also performed IHC staining for SLC7A11 and p-4EBP1 (Ser65) in xenograft tumor samples." (PMID 38842940, 2024). "In addition high expression of SLC7A11 has a significant effect on tumor chemotherapy, radiotherapy, and even immunotherapy." (PMID 39029955, 2024). "Meanwhile, many studies suggest that Erastin (SLC7A11 inhibitor) or RSL3 (GPX4 inhibitor) could inhibit tumor progression and also increasing the chemotherapeutic effect of some chemotherapeutics." (PMID 38600610, 2024). "Additionally, high levels of SLC7A11 expression in HCC are closely linked to lower tumor differentiation, advanced tumor nodular metastasis stage, and unfavorable prognosis." (PMID 38816377, 2024). "Notably, among these regulators, SLC7A11 emerged as a potential immune infiltration-related ferroptosis regulator, shedding light on its role in the tumor microenvironment." (PMID 38655266, 2024). "Targeting GPX4 or SLC7A11 has been shown to reduce tumor growth in different NSCLC model systems." (PMID 39400975, 2024). "Tumor cells with high SLC7A11 expression are highly dependent on glucose for survival." (PMID 39769017, 2024). "SLC7A11 has already been shown to function as a tumor promoter in TNBC." (PMID 38539825, 2024). "The overexpression of SLC7A11 promotes tumor growth partly by inhibiting ferroptosis." (PMID 38383815, 2024). "Additionally, in vivo experiments demonstrated that heightened SLC7A11 expression facilitated localized tumor growth while impeding tumor migration." (PMID 39040097, 2024). "For instance, the expression levels of SLC3A2 and SLC7A11 may correlate with tumor sensitivity to ferroptosis inducers, serving as predictive factors for treatment outcomes." (PMID 39273090, 2024). "Additionally, SLC7A11 gene expression was positively associated with neutrophil and macrophage infiltration, suggesting a potential link between SLC7A11 and tumor immunity." (PMID 38073087, 2024). "This cationic PQDEA effectively complexed anionic SLC7A11 shRNA (shSLC7A11) through the electrostatic interactions, yielding uniform particles with a consistent size of around 65 nm, offering distinct advantages for endocytosis and tumor penetration." (PMID 38399303, 2024). "Differences in the expression levels of SLC7A11 in different tumor tissues, and differences in the expression levels of SLC7A11 between different patients may also be closely related to the temporal, spatial, and individual heterogeneity of tumor tissues." (PMID 39040097, 2024). "Meanwhile, inhibition of SLC7A11 expression may contribute to tumor cell's adaptation to a hypoxic tumor environment, as a result, facilitating tumor development." (PMID 38774759, 2024). "Therefore, the ability of SLC38A5 to potentiate Nrf2 signaling with a resultant increase in SLC7A11 expression is important, underscoring the tumor-promoter role of SLC38A5." (PMID 38539825, 2024). "Additionally, the crucial role of SLC7A11 enables rapid identification of tumor subtypes sensitive to disulfidptosis, facilitating precision therapy." (PMID 39415848, 2024). "Overexpressed SLC7A11 in human tumor cells inhibits ROS-induced “ferroptosis”." (PMID 38469234, 2024).
tumor (continued). "In addition, high overexpression of SLC7A11 enhances primary tumor growth but prevents tumor metastasis, likely because SLC7A11-high cancer cells are vulnerable to oxidative stress-induced cell death during metastasis." (PMID 38705513, 2024). "Moreover, we performed SLC7A11 IHC staining to detect the expression of SLC7A11 in four pairs of matched pathological section of PCa and benign prostate tissue adjacent to tumor from PCa patients." (PMID 38191330, 2024). "However, high overexpression of SLC7A11 can unexpectedly inhibit tumor metastasis, highlighting the dynamic nature of ferroptosis." (PMID 39193375, 2024). "Current studies have shown that disulfidptosis may affect tumor migration and invasion through the high expression of SLC7A11." (PMID 39061076, 2024). "Indeed, we further found that 3-TYP treatment reduced SLC7A11 expression in tumor tissues, which was the reason for the decreased GSH/GSSG ratio in GBM tumors in xenograft mice." (PMID 38395990, 2024). "c-myc can act on SLC7A11 to promote glutamine excretion, in exchange for an increase in intracellular cysteine, which in turn was used for glutathione synthesis, thus protecting tumor cells from oxidative damage." (PMID 38172980, 2024). "The mechanism may be related to the increased sensitivity of tumor cells to ferroptosis by IFN-γ by inhibiting solute carrier family 7 member 11 (SLC7A11) expression." (PMID 39834804, 2024). "Notably, at the protein levels, SLC1A4 and SLC1A5 were highly expressed in most CRC tumors, and SLC7A11 was highly expressed in more than half of tumor samples." (PMID 39079386, 2024). "However, currently SLC7A11 detection is usually invasive, expensive, and based on local tumor tissue, which not only cannot represent the overall situation of the tumor, but also makes it difficult to achieve dynamic observation." (PMID 39350768, 2024). "Our investigation showed a correlation between tumor grading and SLC7A11 expression." (PMID 39350768, 2024). "High SLC7A11 expression may enhance the ability of tumor cells to defend against oxidative stress and promote tumor growth and chemotherapy resistance." (PMID 39014263, 2024). "Therefore, based on the overall tumor, this study constructed a non-invasive radiomics prediction model for SLC7A11, which can achieve prediction of patient prognosis." (PMID 39350768, 2024). "Thus, most tumor cells rely predominantly on SLC7A11 to transport extracellular cystine into the cytoplasm and use nicotinamide adenine dinucleotide phosphate (NADPH) to reduce it back to cysteine." (PMID 39415848, 2024). "As for methylation analyses, we observed that the methylation levels of SLC7A11 were consistently decreased in tumor samples, suggesting that hypomethylation might induce the transcriptional activation of SLC7A11 which results in disulfidptosis." (PMID 38420162, 2024). "Interferon gamma (IFN-γ) released by CD8+ T cells downregulates the expression of two subunits, SLC3A2 and SLC7A11, of the glutamate-cysteine antiporter system, impairing tumor cell uptake of cysteine, thereby promoting lipid peroxidation and ferroptosis in tumor cells." (PMID 38753091, 2024). "In addition, we used many methods and aspects to verify the relationship between SLC7A11 and tumor immunity." (PMID 37880315, 2023). "Additionally, the expression level of SLC7A11 in tumor tissue was compared to the expression in normal tissue." (PMID 37190291, 2023).
tumor (continued). "The anti-tumor cytokine IFN-γ derived from CD8 T cells could downregulate the expression of SLC7A11 and SLC3A2, which further activate the ferroptosis pathway and exhibit anti-tumor effect." (PMID 37587262, 2023). "The effect of elesclomol (ES) on cancer cells is to increase the level of Cu2 + in mitochondria, reduce the expression of ATP7A, lead to Cu2 + retention and the accumulation of ROS, promote SLC7A11 degradation, further enhance oxidative stress in cells and thereby induce tumour cell cuproptosis." (PMID 36600313, 2023). "Of note, the pharmacological blockade of glucose uptake by GLUT inhibitors was proved to exert cancer killing effects by the promoting disulfidptosis in SLC7A11-high tumor cells, highlighting the therapeutic utility of disulfidptosis-induction strategies in cancer treatment." (PMID 37587262, 2023). "Importantly, sulfasalazine, an FDA-approved anti-inflammatory drug, can inhibit SLC7A11, disrupt redox balance, and induce massive ferroptosis, leading to impaired tumor growth in vivo." (PMID 37460542, 2023). "CD8+ T cells downregulate the expression of SLC3A2 and SLC7A11, two subunits of the glutamate–cystine reverse transport system Xc-, by releasing IFNγ, which in turn impairs cystine uptake by tumor cells, promoting tumor cell lipid peroxidation and the onset of ferroptosis." (PMID 36671532, 2023). "Therefore, the overexpression of SLC7A11 in tumour cells can stimulate GSH synthesis and result in ferroptosis resistance." (PMID 37868994, 2023). "On the other hand, SLC7A11 is able to promote tumor progression by inhibiting ferroptosis." (PMID 36874967, 2023). "Furthermore, SLC7A11 was significantly overexpressed in patients who experienced death and in tumor tissues." (PMID 37427103, 2023). "METTL3 promoted LUAD tumor growth by stabilizing SLC7A11 m6A modification." (PMID 37315289, 2023). "In support of our hypothesis, the analysis showed high SLC7A11 expression in 50% (6 of 12) primary tumor samples but only 12% (2 of 16) of the CTCs." (PMID 37339981, 2023). "In addition, recent studies revealed that overexpression of SLC7A11, a protein that imported cysteine for glutathione biosynthesis and antioxidant defense, promotes tumor growth partly through suppressing ferroptosis (Koppula, Zhuang & Gan, 2021)." (PMID 37927794, 2023). "It refers to the fact that, in glucose-starved tumor cells, solute carrier family 7-member 11 (SLC7A11) overexpression leads to a massive depletion of nicotinamide adenine dinucleotide phosphate (NADPH), which in turn triggers an abnormal accumulation of disulfide bonds." (PMID 38139458, 2023). "Interferon gamma (IFNγ) released from CD8+ T cells downregulates the expression of SLC3A2 and SLC7A11, two subunits of the glutamate-cystine antiporter system xc-, impairs the uptake of cystine by tumour cells and, as a consequence, promotes tumor cell lipid peroxidation and ferroptosis." (PMID 38201582, 2023). "Together, our data indicate that, at least in the cell lines or tumor models we have examined, high SLC7A11 overexpression promotes primary tumor growth but suppresses metastasis, likely because SLC7A11-high cancer cells are susceptible to cell death induced by oxidative stress during metastasis." (PMID 37339981, 2023). "Moreover, the conditional ablation of SLC7A11 initiates tumor-selective ferroptosis, which inhibited pancreatic ductal adenocarcinoma growth." (PMID 38562992, 2023).
tumor (continued). "Together, these results indicated that AhR might inhibit tumor cell ferroptosis by regulating SLC7A11 expression." (PMID 37056388, 2023). "BAP1 inhibits tumor development, in part, via SLC7A11 and ferroptosis." (PMID 37061535, 2023). "It has been shown that IFNγ released from CD8+ T cells downregulates the expression of two subunits (SLC3A2 and SLC7A11) of the glutamate-cystine reverse transporter system xc, which inhibits tumor cell cystine uptake and thus promotes lipid peroxidation in tumor cells." (PMID 37399661, 2023). "External immunohistochemical analysis showed that TFRC and SLC7A11 were highly expressed in tumor tissues compared with para-cancer normal tissues, and the expression level was significantly associated with a more advanced stage and worse cancer-specific survival." (PMID 37940859, 2023). "This might help explain, at least partly, the differential effects of SLC7A11 high overexpression in primary tumor growth versus tumor metastasis." (PMID 37339981, 2023). "Additionally, an increasing number of studies have confirmed that SLC7A11 inhibits ferroptosis in tumor cells." (PMID 38017014, 2023). "Uptake of [18F]FSPG in tumor cells is related to protein expression of the xCT transporter, a glutamate–cystine exchanger (SLC7A11/SLC3A2 (4F2hc) heterodimer) that transports L-cystine (Cys-S-S-Cys) into the cell and L-glutamate to the extracellular compartment." (PMID 36961000, 2023). "Notably, FTO-induced hypomethylation drives the downregulation of SLC7A11 expression, promoting tumour ferroptosis." (PMID 36859310, 2023). "Moreover, mRNA and protein levels of KIAA1429 and SLC7A11 were verified in subcutaneous xenograft tumours." (PMID 37830241, 2023). "Moreover, SLC7A11 is highly expressed in tumor cells where it imports cystine for GSH biosynthesis and antioxidant defense." (PMID 37277776, 2023). "The mechanism of SLC7A11 promoting tumor growth has been widely studied." (PMID 37940859, 2023). "This is because targeting SLC7A11 may allow for the selective killing of tumor cells and the impediment of tumor growth while sparing normal cells or tissues." (PMID 37598126, 2023). "Similar results can be observed by IHC staining of ACSL4, GPX4, and SLC7A11 in subcutaneous tumor." (PMID 37993428, 2023). "Consequently, sh‐KIAA1429 notably mitigated tumour growth and weight, which was partially reversed by Lv‐SLC7A11." (PMID 37830241, 2023). "It was found that upregulation of SLC7A11 gene expression could activate AP-1 transcription factor, which could affect tumor uptake and metabolism of calcium ions and accelerate its cell cycle to promote tumor growth and proliferation." (PMID 37399661, 2023). "Similarly, compared to that in peritumor tissues, the expression of ferroptosis-inducing genes, including PTGS2, HMOX1, TFR2, and NCOA4, was down-regulated in tumor tissues, whereas ferroptosis-suppressor genes SLC7A11 and FTH1 were upregulated." (PMID 37554285, 2023). "SLC7A11 has emerged as a critical factor linking ferroptosis to its tumor suppressor function." (PMID 38017014, 2023). "Furthermore, a high SLC7A11 expression rescues the decrease in tumour weight and volume mediated by VD in vivo." (PMID 36846715, 2023). "Depleting SLC7A11 expression hampers tumor sphere formation and increases oxidative stress." (PMID 37298344, 2023). "Similarly, SLC7A11 inhibition-derived ferroptosis has been described as an escape mechanism for tumor growth in CRC." (PMID 37686618, 2023).
tumor (continued). "However, there is still an incomplete understanding of how tumor cells maintain high levels of SLC7A11." (PMID 37552314, 2023). "In addition, previous studies have shown that SLC7A11-mediated extracellular glutamate accumulation not only serves as a raw material for cancer cell growth but also plays an essential role in tumour migration and invasion." (PMID 37919768, 2023). "In addition, the release of interferon-γ from activated CD8+ T cells can inhibit SLC7A11, thus further activating the ferroptosis pathway to play an anti-tumor effect." (PMID 38137387, 2023). "In addition, immunotherapy can enhance the efficacy of radiotherapy, which cooperatively inhibits SLC7A11 to induce ferroptosis of tumor cells." (PMID 37714846, 2023). "In 786-O xenograft tumor models, SLC7A11-high tumors exhibited significantly increased tumor growth compared with SLC7A11-moderate or -low tumors, which was consistent with our and others’ previous findings revealing a role of SLC7A11 in promoting tumor growth." (PMID 37339981, 2023). "Interestingly, because tumor cells are often exposed to high levels of oxidative stress, SLC7A11 is more important for enhancing their antioxidant defense and inhibiting ferroptosis, which is beneficial for tumor growth." (PMID 37564206, 2023). "Furthermore, GRh3 prevented NRF2 from entering the nucleus, which suppressed xCT/SLC7A11, causing the depletion of GSH and the accumulation of iron, lipid ROS and MDA, and eventually leading to ferroptosis in tumor cells." (PMID 37092860, 2023). "SLC7A11 also promotes tumour cell metastasis by inhibiting iron-related death in various cancers." (PMID 37829798, 2023). "However, targeted inhibition of SLC7A11 or GPX4 has been shown to sensitize tumor cells to radiotherapy, leading to increased effectiveness." (PMID 37980334, 2023). "Inhibition of SLC7A11 could enhance the tumor-killing effect of immune cells and sensitize cancer cells’ responsiveness to immunotherapies." (PMID 37587262, 2023). "Such as the ferroptosis inducer sulfasalazine which targets SLC7A11 might be effective against tumor cells overexpressing SLC7A11." (PMID 37061535, 2023). "Professor Ganboyi's research demonstrates that elevated expression of SLC7A11 promotes metabolic vulnerability‐induced disulphide death in cancer cells, which could be an effective strategy for tumour treatment." (PMID 37927242, 2023). "SLC7A11 made tumor cells highly dependent on glucose and glutamine." (PMID 37329384, 2023). "SLC7A11 is overexpressed in multiple human cancers and promotes tumor survival." (PMID 37005430, 2023). "These two features of SLC7A11, its non-essential nature in normal physiology and its high expression in cancer, suggest that targeting SLC7A11 may selectively kill tumor cells and impair tumor growth while preserving normal cells or tissues." (PMID 36874967, 2023). "Mechanistically, the authors showed that activated CD8 T cells released the effector cytokine, interferon gamma (IFNγ), which upon binding to cancer cells triggered the downregulation of SLC7A11 expression, thereby impairing cystine uptake and resulting in lipid peroxidation and tumor ferroptosis." (PMID 35065965, 2022). "Next, to determine whether SLC7A11 was essential for the YY2 tumor suppressive effect, we performed xenograft experiments using a stable HCT116 cell line overexpressing both YY2 and SLC7A11." (PMID 35246964, 2022). "The same study showed that the ATF4 factor is responsible for the regulation of glutamate antiporter xCT (SLC7a11) expression, which is a critical tumor-induced intoxication of the brain’s microenvironment, and glutamate secretion in human malignant glioma specimens." (PMID 35409080, 2022).